FUT8 (fucosyltransferase 8)
Description:
Catalyzes the addition of fucose in alpha 1-6 linkage to the first GlcNAc residue, next to the peptide chains in N-glycans. Fucosylates the reducing GlcNAc residue in complex-type N-glycans attached on the fragment crystallizable (Fc) of IgGs. Fully converts Fc glycoforms containing one or two terminal GlcNAc moieties (G0-GlcNAc and G0).
Synonyms: CDGF; CDGF1
Tractability: Small molecule: a structure with a bound ligand is known; it has a binding pocket of medium quality. Antibody: UniProt predicts a signal peptide or a membrane-spanning region. PROTAC: ubiquitination databases record sites on it; its protein half-life has been measured; a small molecule that binds it is known.
Target class: Enzyme; Transferase
Gene: Protein-coding gene on chromosome 14 (65,410,592 to 65,744,125, forward strand). Ensembl gene ENSG00000033170.
Subcellular location: Golgi apparatus, Golgi stack membrane
Subcellular location (Human Protein Atlas): Golgi apparatus; Cytosol; Nucleoplasm
Pathways (Reactome):
Disease: Maturation of spike protein
Metabolism of proteins: Reactions specific to the complex N-glycan synthesis pathway
Gene Ontology:
Molecular function: glycoprotein 6-alpha-L-fucosyltransferase activity; protein binding; alpha-(1->6)-fucosyltransferase activity
Biological process: GDP-L-fucose metabolic process; protein N-linked glycosylation; in utero embryonic development; L-fucose catabolic process; N-glycan processing; oligosaccharide biosynthetic process; viral protein processing; glycoprotein biosynthetic process; protein O-linked glycosylation via fucose
Cellular component: extracellular exosome; membrane; Golgi apparatus; Golgi membrane; Golgi cisterna membrane
Genetic constraint (gnomAD): Loss-of-function variants: 27 observed, 55.86 expected, observed/expected ratio (o/e) 0.48, 90% interval 0.35 to 0.67. The upper end of that interval is the gene's LOEUF score, 0.67, which puts it in group 2 of 6, group 1 being the genes least tolerant of losing a copy. Missense variants: 489 observed, 645.66 expected, observed/expected ratio (o/e) 0.76, 90% interval 0.7 to 0.82. Synonymous variants: 221 observed, 220.23 expected, observed/expected ratio (o/e) 1, 90% interval 0.9 to 1.12.
Gene-disease validity (ClinGen):
ClinGen rates the evidence that FUT8 causes each of these diseases.
congenital disorder of glycosylation with defective fucosylation 1 (autosomal recessive): Definitive.
Homologues: Orthologues: chimpanzee FUT8 (100% identical), macaque FUT8 (99% identical), rabbit FUT8 (98% identical), guinea pig FUT8 (98% identical), rat Fut8 (97% identical), mouse Fut8 (97% identical), pig FUT8 (96% identical), tropical clawed frog fut8 (91% identical), zebrafish fut8a (81% identical), zebrafish fut8b (78% identical), Drosophila melanogaster FucT6 (49% identical), Caenorhabditis elegans fut-8 (36% identical).
Diseases named in the same sentence as FUT8 in open-access papers:
FUT8 is named in the same sentence as 115 diseases in open-access papers, as found by Europe PMC text mining. Sharing a sentence is not in itself a finding about the gene and the disease. The quoted sentences say what the papers report.
breast carcinoma (32 papers, 2013 to 2025). "Loss-of-function studies demonstrated that FUT8 knockout suppressed the invasiveness of highly aggressive breast carcinoma cells." (PMID 35303925, 2022). "FUT8 has been linked to the migratory and invasive capabilities of aggressive breast cancer cell lines, and identified as highly upregulated in TGFβ-induced EMT." (PMID 33466384, 2021). "A recently published meta-analysis showed that FUT8 expression levels are associated with the overall survival of breast cancer, non-small-cell lung cancer, glioma, diffuse large B-cell lymphoma, and gastric cancer." (PMID 34093814, 2021). "In agreement with this expression profile, in silico Kaplan-Meier survival analysis of three public microarray datasets revealed that high FUT8 levels were associated with poor prognosis in breast cancer." (PMID 28982386, 2017). "Together, these findings imply that FUT8 upregulation is associated with cancer cell invasiveness and poor prognosis in breast cancer, which agrees with a recent report." (PMID 28982386, 2017). "These FUT8 glycoproteins provide a resource for further understanding molecular mechanisms underlying breast cancer invasion and metastasis and are potential targets for preventing and treating metastatic breast cancers." (PMID 35303925, 2022). "The elevated FUT8 level in breast cancer has been found to be associated with lymphatic metastasis." (PMID 28798691, 2017). "Recently, FUT8 expression was found to be associated with poor prognosis in breast cancer." (PMID 28982386, 2017). "Lentivirus-mediated gain-of-function study, short hairpin RNA (shRNA) or CRISPR/Cas9-mediated loss-of-function studies and pharmacological inhibition of FUT8 were used to elucidate the molecular function of FUT8 during TGF-β-induced EMT in breast carcinoma cells." (PMID 28982386, 2017). "Although the precise molecular mechanism underlying the upregulation of FUT8 during TGF-β-induced EMT remains elusive in breast carcinoma cells, FUT8 may be modulated in part at the transcriptional level because its mRNA level is highly induced in TGF-β-induced EMT." (PMID 28982386, 2017). "FUT8-mediated core fucosylation modification of the B7H3 protein promotes immune escape in breast cancer and triple-negative breast cancer (TNBC)." (PMID 40373023, 2025). "This was in accordance with the report that FUT8 expression was elevated in breast cancer through transcription factor activator protein 2γ regulation." (PMID 38575942, 2024). "One proposed mechanism of FUT8 induction in breast cancer has been recognized upon TGFβ-induced EMT." (PMID 36980181, 2023). "Another work has unveiled a FUT8 regulatory axis in breast cancer based on the transcription factor activator protein 2γ (AP-2γ) binding to the Signal Transducer and Activator of Transcription 3 (STAT3)." (PMID 36980181, 2023). "Overexpression of FUT8 and core fucosylation was observed in several cancers, such as lung and breast cancers." (PMID 35833116, 2022). "We recently showed that fucosyltransferase 8 (FUT8)-mediated core fucosylation of transforming growth factor-β receptor enhances its signaling and promotes breast cancer invasion and metastasis." (PMID 35303925, 2022). "The reduced invasiveness caused by FUT8 knockdown in SW480 cells has been described previously in melanoma, pancreatic, lung, and breast cancer, among others." (PMID 35955598, 2022). "To search for additional FUT8 target glycoproteins and their downstream signaling during breast cancer progression, we used stable isotope labeling by amino acids in cell culture (SILAC)-based quantitative glycoproteomics." (PMID 35303925, 2022). "We first established FUT8-KO cell lines from two highly invasive breast cancer cell lines, MDA-MB-231 and Hs578T, by using the CRISPR-Cas9 system." (PMID 35303925, 2022). "Together, these results further verify that the FUT8 target glycoproteins we identified indeed have broader pathological involvement in cancer types beyond breast cancer." (PMID 35303925, 2022).
breast carcinoma (continued). "We performed quantitative glycoproteomics with two highly invasive breast cancer cell lines to unravel a comprehensive list of core-fucosylated glycoproteins by comparison to parental wild-type and FUT8-knockout counterpart cells." (PMID 35303925, 2022). "FUT8, whose expression level is positively related to a higher tumor stage and lymph node metastasis, is overexpressed in breast cancer." (PMID 35216622, 2022). "These FUT8 targets reveal a global and novel aspect of signaling pathways and networks essential for breast cancer migration, invasion, and metastasis." (PMID 35303925, 2022). "We identified glycoproteins differentially expressed in core fucose-specific lectin Lens culinaris agglutinin (LCA)-enriched fractions from aggressive breast cancer cells and compared these to their FUT8-KO counterparts." (PMID 35303925, 2022). "The FUT8 target glycoproteins in breast cancer we identified in general agree with those in previous studies of melanoma or non-small cell lung cancer by sharing greater than 78% coverage." (PMID 35303925, 2022). "FUT8 promotes breast cancer cell invasiveness by remodeling tansforming growth factor-beta (TGF-β) receptor core fucosylation." (PMID 33976130, 2021). "The results revealed that FUT8 was one of the most significantly upregulated fucosyltransferase genes in breast cancer tissues." (PMID 33976130, 2021). "In breast cancer, upregulated FUT8 remodels TGF-β RI and RII complexes to promote downstream signalling, and genetic or pharmacological interruption of FUT8 inhibits TGF-β signalling and suppresses breast cancer metastasis in vivo." (PMID 33466384, 2021). "Recent studies indicate that FUT8 expression levels are highly correlated with cancer development, in particular, hepatocellular carcinoma, melanoma, breast cancer, and gastric cancer." (PMID 34857735, 2021). "In line with our data, higher FUT8 protein expression was found to be correlated with lymphatic metastasis in breast carcinoma tissues." (PMID 34703796, 2021). "FUT8 promotes breast cancer cell invasiveness by remodeling TGF-β receptor core fucosylation and drives the proliferation and invasion of trophoblastic cells via the Insulin-like growth factor 1 (IGF-1)/IGF-1R signaling pathway." (PMID 31022917, 2019). "By remodelling the TGF-β receptor core fucosylation, FUT8 expression influences breast cancer invasiveness." (PMID 31308057, 2019). "Interestingly, higher expressions of the glycosyltransferases responsible for core fucosylation (FUT8), branching (GnT-V), and sialylation (both α-2, 3 and α-2, 6 sialytransferases) have been associated with a greater potential for motility, invasion and metastasis in breast cancer." (PMID 31208374, 2019). "Studies directly evaluating the contribution of FUT8, which regulates core fucosylation, to breast cancer progression are limited." (PMID 31126011, 2019). "The 4T1 mammary tumor metastasis model was used to evaluate the effect of Fut8 knockdown in vivo and showed that lung metastasis was reduced with the loss of Fut8." (PMID 31126011, 2019). "FUT8 promotes breast cancer cell invasiveness by remodeling TGF-β receptor core fucosylation and FUT4 is an effective biomarker for the diagnosis of breast cancer." (PMID 30619732, 2018). "In brief, fentanyl promotes FUT8 expression and FUT8-catalyzed α1, 6-fucosylation level in breast cancer cells." (PMID 28798691, 2017). "Our results unravel a novel feed-forward mechanism of FUT8-mediated TGF-β receptor core fucosylation that stimulates breast cancer cell invasion and metastasis." (PMID 28982386, 2017). "FUT8 was upregulated during TGF-β-induced EMT in breast carcinoma cells and upregulated FUT8 remodeled the core-fucosylated N-glycans on cell-surface targets such as TGF-β RI and RII complexes to enhance ligand binding and promote downstream signal activity." (PMID 28982386, 2017). "Our genetic studies clearly demonstrated that FUT8 plays an essential role in breast cancer invasion and metastasis." (PMID 28982386, 2017).
breast carcinoma (continued). "Nevertheless, more investigations are required to further validate the molecular function of SNAIL in FUT8 upregulation with TGF-β treatment in the context of breast carcinoma cells." (PMID 28982386, 2017). "In this study, we identified that FUT8 is highly upregulated in TGFβ-induced EMT and associated with the migratory and invasive ability of aggressive breast carcinoma cell lines." (PMID 28982386, 2017). "The role of FUT8 in breast cancer migration, invasion, and metastasis was confirmed using an in vitro transwell assay and mammary fat pad xenograft in vivo tumor model." (PMID 28982386, 2017). "Gain-of-function and loss-of-function studies demonstrated that FUT8 overexpression stimulated the EMT process, whereas FUT8 knockdown suppressed the invasiveness of highly aggressive breast carcinoma cells." (PMID 28982386, 2017). "Gene expression profiling analysis revealed that FUT8 is upregulated in TGF-β-induced EMT; the process was associated with the migratory and invasive abilities of several breast carcinoma cell lines." (PMID 28982386, 2017). "Further understanding the signaling and biological effects of core fucosylation on these target glycoproteins will help decipher the complex molecular mechanisms of FUT8 in breast cancer progression." (PMID 28982386, 2017). "To assess the effects of FUT8 in breast cancer phenotypes, we first knockdown the expression of FUT8 in MCF-7 cells, and the knockdown efficiency was verified by Western blot and immunofluorescent staining." (PMID 28798691, 2017). "Increased expression of these genes also correlated with a decreased risk of breast cancer recurrence, although only four (RABEP1, PGR, SLC39A6 and FUT8) exhibited significant adjusted p-values." (PMID 23819905, 2013). "Similarly, FUT4 has been proposed as a marker for breast cancer, and expression of FUT8 is positively correlated with migration and invasiveness of breast cancer cells and lung cancer." (PMID 40642090, 2025). "In addition, FUT8 interference reduced the expression of metalloproteinase 2, and especially metalloproteinase 9, in breast cancer cells, impairing the extracellular matrix reorganization required for tumor spread." (PMID 35955598, 2022). "To identify novel FUT8 target glycoproteins and their signaling pathways involved in breast cancer cell invasiveness, we used SILAC-based quantitative proteomic analyses to measure the differences in the core-fucosylated proteins between parental and FUT8-KO MDA-MB-231 or Hs578T cells." (PMID 35303925, 2022). "More specifically the level of FUT8 expression was correlated with miR-10 b co-upregulation via the transcription factor Twist or the transcription factor activator protein 2γ (AP-2γ) in breast cancer cells." (PMID 36699698, 2022). "Studies have shown that the core fucose level is increased in tumor tissues compared with normal tissues and that the aberrant expression of FUT8 promotes the proliferation and invasion of malignant tumors such as liver cancer, breast cancer, and non-small cell lung cancer." (PMID 36499043, 2022). "In addition, it has been shown that down-regulation of the FUT8 expression inhibits the invasion and migration ability of breast cancer cells." (PMID 36499043, 2022). "To investigate the most enriched biological functions and molecular networks of FUT8 targets in invasive breast cancer cells, we used disease and function analysis of the two sets of FUT8 target glycoproteins with QIAGEN Ingenuity Pathway Analysis (IPA) software." (PMID 35303925, 2022). "Another intriguing finding was that the FUT8 target glycoproteins associated with any given functional category were not necessarily identical between these two breast cancer cell lines, yet they are involved in the same molecular and cellular functions." (PMID 35303925, 2022). "Therefore, we need to identify additional FUT8 target proteins and their downstream signaling during breast cancer progression." (PMID 35303925, 2022).
breast carcinoma (continued). "We recently identified FUT8 as a key regulator during breast cancer metastasis." (PMID 35303925, 2022). "However, the full spectrum of FUT8 target glycoproteins and a comprehensive network of signaling pathways orchestrated by FUT8 for breast cancer cell migration and invasion leading to metastasis remain elusive and uninvestigated." (PMID 35303925, 2022). "The upregulated expression of FUT8 has been reported in several cancers, including breast cancer, lung cancer, prostate cancer, hepatocellular carcinoma, colorectal cancer, and melanoma, demonstrating that FUT8 is involved in biological tumor characteristics and patient outcomes." (PMID 33976130, 2021). "However, studies show that FUT8 expression in breast cancer patient samples correlated with lymph node metastasis, disease-free survival and overall survival." (PMID 31126011, 2019). "FUT8, the gene encoding the only enzyme responsible for core-fucose modification was shown to have a higher expression level in highly invasive MDA-MD-231 breast cancer cells." (PMID 31126011, 2019). "We found that FUT8 expression was significantly elevated in breast cancer vs. normal samples (p < 0.0001), supporting our current findings that core-fucosylation is a driving factor in breast cancer progression." (PMID 31126011, 2019). "This suppressive TGF-β1 signaling activity could be fully rescued by overexpression of FUT8 by a recombinant lentiviral vector, which demonstrates the critical and specific involvement of FUT8 in TGF-β1 activity in breast cancer MDA-MB-231 cells." (PMID 28982386, 2017). "In addition, gain-of-function and loss-of-function studies have demonstrated that FUT8 overexpression stimulates EMT, whereas FUT8 knockdown suppresses the invasiveness of highly aggressive breast carcinoma cells." (PMID 28982386, 2017). "Therefore, an important aspect we are actively pursuing is to identify other FUT8 target proteins and how core fucosylation regulates a specific glycoprotein to particulate in a particular signaling and phenotype during breast cancer EMT." (PMID 28982386, 2017). "Furthermore, we confirmed that TGF-β RI and RII are indeed FUT8 target proteins and can be core-fucosylated in aggressive breast carcinoma cells because FUT8 knockout completely eliminated its core fucosylation." (PMID 28982386, 2017). "Because FUT8 knockdown inhibited highly invasive 4T1 breast cancer cell invasion in vitro, we next examined whether it could suppress breast tumor metastasis in vivo." (PMID 28982386, 2017). "Importantly, FUT8 inhibition suppressed the invasive ability of highly metastatic breast cancer cells and impaired their lung metastasis." (PMID 28982386, 2017). "Based on these findings, we speculate that FUT8 and α 1, 6-fucosylation may serve as potential targets for breast cancer treatment." (PMID 28798691, 2017). "To determine whether the β-catenin/LEF-1 pathway indeed participates in regulating FUT8 expression in breast cancer cells, we examined the effect of shRNA-mediated β-catenin knockdown on the expression of FUT8 in MDA-MB-231 cells." (PMID 28982386, 2017). "However, the complete FUT8 target glycoproteins and their downstream signaling networks critical for breast cancer progression remain largely unknown." (PMID 35303925, 2022). "However, as far as we know, even though the role of FUT8 has been investigated in many cancers such as lung cancer, prostate cancer, and breast cancer, the relationship between FUT8 and the progression of OS has received no investigative attention before our study." (PMID 34857735, 2021). "Importantly, pharmacological inhibition by a small molecule inhibitor, 2-fluorinated-peracetyl-fucose (2 F-peracetyl-fucose), or genetic inactivation of FUT8 suppressed the invasive ability of aggressive breast cancer cells in vitro and impaired their lung metastasis in vivo." (PMID 28982386, 2017).